NTMT1 (N-terminal Xaa-Pro-Lys N-methyltransferase 1)
Diseases named in the same sentence as NTMT1 in open-access papers:
NTMT1 is named in the same sentence as 33 diseases in open-access papers, as found by Europe PMC text mining. Sharing a sentence is not in itself a finding about the gene and the disease. The quoted sentences say what the papers report.
breast carcinoma (3 papers, 2015 to 2018). "Knockdown of NTMT1 results in hypersensitivity of breast cancer cell lines to double-stranded DNA breaks (DSBs) and increased proliferation of estrogen receptor positive breast cancer cells MCF-7 and LCC916; NTMT1 knockout mice are phenotypically defective in DNA repair and exhibit premature aging." (PMID 30417120, 2018).
glioma (2 papers, 2022 to 2023). A benign or malignant brain and spinal cord tumor that arises from glial cells (astrocytes, oligodendrocytes, ependymal cells). "The results suggest that NTMT1 expression is positively associated with various cellular functions, such as cell cycle, DNA damage, DNA repair, invasion metastasis, and apoptosis in ALL, AML, CML, CRC, BRCA, AST, GBM, Glioma, HGG, ODG, HNSCC, LUAD, NSCLC, OV, and MEL." (PMID 37901469, 2023).
cervical cancer (1 paper, 2023). A primary or metastatic malignant neoplasm involving the cervix. "In cervical cancer, high levels of NTMT1 expression have been associated with poorer prognosis and increased tumor aggressiveness." (PMID 37901469, 2023). "In other types of cancer, such as cervical cancer and colorectal cancer, NTMT1 has been found to act as an oncogene, promoting the migration and growth of cancer cells." (PMID 37901469, 2023). "Meanwhile, it has been suggested that NTMT1 promotes cervical cancer cell migration by upregulating ELK3." (PMID 37901469, 2023).
colorectal cancer (1 paper, 2023). A primary or metastatic malignant neoplasm that affects the colon or rectum. "Additionally, CALR is clinically associated with high survival rates in colorectal cancer patients, indicating that a combination of NTMT1 protein degradation drugs and immune checkpoint therapy may improve the efficacy of tumor treatment." (PMID 37901469, 2023).
head and neck squamous cell carcinoma (1 paper, 2023). A squamous cell carcinoma that arises from any of the following anatomic sites: lip and oral cavity, nasal cavity, paranasal sinuses, pharynx, larynx, and salivary glands. "In this study, the expression of NTMT1 in a variety of tumors was investigated using bioinformatics techniques, with particular emphasis on its role in the development and progression of head and neck squamous cell carcinoma (HNSCC) and its relationship with immunity." (PMID 37901469, 2023).
melanoma (1 paper, 2022). A malignant, usually aggressive tumor composed of atypical, neoplastic melanocytes. "NRMT, also known as NTMT1, is demonstrated as an oncogene in diverse human cancers such as melanoma, gastrointestinal and brain malignancies." (PMID 35013138, 2022).
paraganglioma (1 paper, 2023). A benign or malignant neoplasm arising from paraganglia located along the sympathetic or parasympathetic nerves. "Conversely, NTMT1 was significantly down-regulated in kidney renal clear cell carcinoma (KIRC) and pheochromocytoma and paraganglioma (PCPG)." (PMID 37901469, 2023).
cancer (11 papers, 2015 to 2025). A tumor composed of atypical neoplastic, often pleomorphic cells that invade other tissues. "NTMT1 expression is upregulated in several cancers, including HNSCC, and its overexpression has been associated with increased tumor growth and invasion." (PMID 37901469, 2023). "Our analysis revealed that NTMT1 exhibited a high degree of diagnostic accuracy for eight types of cancer (AUC > 0.9), including PCPG, CHOL, COAD, READ, DLBC, LAML, TGCT, and THYM." (PMID 37901469, 2023). "To assess the diagnostic value of NTMT1 in pan-cancer, we performed a receiver operating characteristic (ROC) curve analysis based on data from the Cancer Genome Atlas (TCGA) database." (PMID 37901469, 2023). "However, further research is required to better comprehend the molecular mechanisms underlying the role of NTMT1 in these cancers and to evaluate the potential of NTMT1-targeted therapies for cancer treatment." (PMID 37901469, 2023). "The overall mutation frequency of NTMT1 in pan-cancer is only 2.4%." (PMID 37901469, 2023). "The underlying regulatory mechanism of NTMT1 in cancer is complex, and it may be involved in both the promotion of tumor development and the inhibition of the tumor immune microenvironment." (PMID 37901469, 2023). "However, the AUC value of 0.878 for HNSCC suggests that NTMT1 expression has only a moderately accurate diagnostic value for HNSCC compared to the other types of cancer." (PMID 37901469, 2023). "NTMT1 has also been implicated in carcinogenesis, but whether it acts as a tumour-suppressor or an oncogene depends on the pathways driving cancer formation in the given tissue." (PMID 32680559, 2020). "Mutations which impact the enzymatic activity of NTMT1 have been detected in cancer." (PMID 32680559, 2020). "A subset of METTLs, such as METTL1, METTL7B, and NTMT1, which had higher frequency of gene alterations/overexpression in various cancers and/or were associated with poor disease prognosis, might function as cancer-promoters." (PMID 34285249, 2021). "This information can help elucidate the function of NTMT1 in biological processes and diseases and potentially identify new therapeutic targets for cancer treatment." (PMID 37901469, 2023). "This study utilized comprehensive bioinformatics analysis techniques to investigate the expression level, clinical prognostic value, immune relevance, and functional enrichment of NTMT1 in pan-cancer." (PMID 37901469, 2023). "Our findings provide a foundation for further research into the specific mechanisms of NTMT1 in different tumor development and treatment, suggesting its potential as an important target for cancer treatment and immunotherapy." (PMID 37901469, 2023). "The analysis of uniform TCGA_GTEx data collected from UCSC also revealed a significant up-regulation of NTMT1 in various types of cancer tissues, which was largely consistent with the results obtained from TCGA." (PMID 37901469, 2023). "Researchers are actively exploring the potential of developing NTMT1-targeted therapies for cancer treatment." (PMID 37901469, 2023). "Further research is needed to fully understand the clinical significance of NTMT1 in HNSCC and to identify potential therapeutic strategies targeting NTMT1 in this cancer type." (PMID 37901469, 2023). "Taken together, NTMT1 plays a complex and context-dependent role in cancer initiation and progression." (PMID 37901469, 2023). "Further verification of the biological functions and regulatory mechanisms of NTMT1 is necessary to better understand its role in cancer and can provide new ideas and strategies for cancer treatment and prognosis evaluation." (PMID 37901469, 2023).
cancer (continued). "In this study, the expression of NTMT1 was analyzed in 33 cancer datasets obtained from the TCGA database." (PMID 37901469, 2023). "Considering the significant breakthroughs in immunotherapy in cancer treatment in recent years, the correlation between NTMT1 and tumor immune infiltration is crucial." (PMID 37901469, 2023). "In this study, we explored the potential role of NTMT1 in cancer using pan-cancer bioinformatic analysis." (PMID 37901469, 2023). "NTMT1 expression is dysregulated in various types of cancer, and its overexpression or underexpression has been associated with different types of cellular functions." (PMID 37901469, 2023). "Initially, we examined the relationship between NTMT1 expression and OS in 33 different types of cancer." (PMID 37901469, 2023). "To evaluate the prognostic significance of NTMT1 in pan-cancer, we conducted a Kaplan–Meier survival analysis to investigate the correlation between NTMT1 expression and clinical outcomes." (PMID 37901469, 2023). "The exact mechanisms by which NTMT1 promotes or suppresses cancer development and progression are not yet fully understood." (PMID 37901469, 2023). "According to the results of Gene Expression Profiling Interactive Analysis (GEPIA), NRMT (named NTMT1 in NCBI) was abnormally overexpressed in 19 (57.6%) of 33 cancers." (PMID 35013138, 2022). "It would be interesting to test cellular impacts of these NTMT1 inhibitors on cancer cells in the future." (PMID 34285249, 2021). "We identified a subset of METTL genes, notably METTL1, METTL7B, and NTMT1, with high frequencies of genomic amplification and/or up-regulation at both the mRNA and protein levels in a spectrum of human cancers." (PMID 34285249, 2021). "Of the 30 METTLs, expressions of eight (METTL1, METTL7B, METTL5, NTMT1, METTL2A, METTL2B, EEF1AKNMT, METTL6) were significantly (FDR < 0.05) associated with unfavorable overall survival across cancers." (PMID 34285249, 2021). "The robust upregulation of NTMT1 that has been reported in different cancer types and its significance in promoting cell proliferation suggest a role of NTMT1 as an oncoprotein." (PMID 32680559, 2020). "Pan-cancer analysis revealed NTMT1 high amplification in ESCA, PAAD, BRCA, OV, and SARC." (PMID 37901469, 2023). "However, further research is required to gain a better understanding of the functions of NTMT1 in cancer development and to assess the potential of NTMT1-targeted therapies for cancer treatment." (PMID 37901469, 2023). "In conclusion, this study has explored the important role of NTMT1 in cancer." (PMID 37901469, 2023). "The potential mechanisms by which NTMT1 could contribute to the development and progression of these cancers are not yet fully understood and require further investigation." (PMID 37901469, 2023). "Moreover, the expression of NTMT1 in 18 types of tumors with paired samples in TCGA was examined, and NTMT1 was found to be significantly up-regulated in 12 types of cancer tissues." (PMID 37901469, 2023). "We performed a co-expression analysis on NTMT1 and immune-related genes associated with immunoinhibitors, immunostimulators, MHC molecules, tumor-infiltrating lymphocytes, chemokines, and chemokine receptors in pan-cancer." (PMID 37901469, 2023). "However, further research is needed to fully elucidate the functional significance of NTMT1 expression in cancer and its potential as a therapeutic target." (PMID 37901469, 2023). "However, further research is needed to fully understand the clinical implications and to determine the potential utility of NTMT1 as a therapeutic target in these cancers." (PMID 37901469, 2023). "However, further research is needed to fully understand the clinical implications of these findings and to determine the potential utility of NTMT1 as a therapeutic target in these cancers." (PMID 37901469, 2023).
cancer (continued). "We also extracted representative immunohistochemistry (IHC) images of the tumor and normal tissues from HNSCC and BRCA, suggesting that NTMT1 may play a critical role in the development and progression of these types of cancer." (PMID 37901469, 2023). "However, the functional understanding of NTMT1's role in cancer progression and prognosis is limited making it a focus of research." (PMID 25914051, 2015). "Similar to NatA subunits, aberrant expression of NTMT1 has been reported in numerous cancer types." (PMID 25914051, 2015). "The reduced expression of multiple immune markers in the high NTMT1 expression group could indicate a weakened immune response against cancer cells, suggesting that NTMT1 may be involved in the evasion of immune surveillance and thus promoting the progression and metastasis of HNSCC." (PMID 37901469, 2023). "Overall, these findings suggest that NTMT1 expression may play a complex and context-dependent role in cancer biology, potentially affecting multiple cellular processes that contribute to the development and progression of cancer." (PMID 37901469, 2023). "Furthermore, NTMT1 expression could serve as a valuable prognostic biomarker in these cancer types, which could help improve patient outcomes through earlier detection and personalized treatment approaches." (PMID 37901469, 2023). "Therefore, the positive correlation between NTMT1 expression and cell proliferation in HNSCC may indicate that NTMT1 could be a potential therapeutic target for this cancer type." (PMID 37901469, 2023). "Additionally, targeting NTMT1 may enhance the effectiveness of immunotherapies by modulating the immune response in these cancers." (PMID 37901469, 2023). "In summary, transcriptomic and proteomic profiles of METTLs across a broad range of cancer types and their associations with clinical outcomes indicated that a subset of METTLs, such as METTL1, METTL7B, and NTMT1, might act as oncogenes, while METTL7A acts as a tumor suppressor." (PMID 34285249, 2021). "The specific role and potential mechanisms of NTMT1 in human cancer are not yet clear and require further exploration." (PMID 37901469, 2023). "Nevertheless, our previous analysis showed a positive correlation between high NTMT1 expression and poor overall survival in HNSCC patients, indicating that NTMT1 may have prognostic value in this cancer type." (PMID 37901469, 2023). "Our analysis revealed that, in the majority of cancers, there were negative correlations between NTMT1 and chemokine receptors." (PMID 37901469, 2023). "Additionally, the T-SNE plot displays the single-cell level expression profiles of NTMT1 in HNSCC, indicating that there are differences in NTMT1 expression among these cancer types at the single-cell level." (PMID 37901469, 2023). "However, it should be noted that future studies are needed to address the pathophysiological significance and molecular mechanisms of the identified METTLs, such as METTL1, NTMT1, and METTL26, in promoting cancer development and progression." (PMID 34285249, 2021). "The results of functional enrichment analysis indicate that genes co-expressed with NTMT1 are mainly involved in biological processes such as immune response, and activation of NF-κB and MAPK signaling pathways, which are closely related to the occurrence and development of cancer." (PMID 37901469, 2023). "However, in most cancers, including HNSCC, NTMT1 is negatively correlated with chemokine receptors." (PMID 37901469, 2023). "We identified a subset of METTL genes, notably METTL1, METTL2A, METTL2B, METTL7B, NTMT1, and METTL26, with high frequencies of genomic amplification and/or up-regulation, while METTL7A and METTL24 were under-expressed, at both mRNA and/or protein levels in a spectrum of human cancers." (PMID 34285249, 2021).
cancer (continued). "Additionally, our study revealed that NTMT1, which methylates the α-N-terminal amines of proteins [e.g., RCC1 (regulator of chromosome condensation 1), CENPA (centromere protein A), and DDB2 (damage specific DNA binding protein 2)], likely possesses cancer-promoting roles." (PMID 34285249, 2021). "Conversely, we observed negative correlations between NTMT1 and immune-related genes in HNSCC, KICH, and COAD, suggesting that immunotherapy may not be as effective in these cancers." (PMID 37901469, 2023).
tumor (8 papers, 2015 to 2026). "Single-cell functional analysis of tumors reveals that NTMT1 is associated with various biological behaviors of tumor cells, such as stemness, invasion, proliferation, metastasis, apoptosis, and EMT, which promote tumor development." (PMID 37901469, 2023). "We further investigated the protein expression levels of NTMT1 in both normal and tumor tissues of various human organs using the HPA." (PMID 37901469, 2023). "NTMT1, a transfer methylase that adds methyl groups to the N-terminus of proteins, has been identified as a critical player in tumor development and progression." (PMID 37901469, 2023). "In this study, we investigated the methylation status of the NTMT1 gene in normal and tumor tissues by comparing the methylation levels of the NTMT1 promoter region." (PMID 37901469, 2023). "In this study, we knocked down NTMT1 gene expression and found that it significantly inhibited tumor cell proliferation, induced DNA damage, and ultimately promoted tumor cell apoptosis." (PMID 37901469, 2023). "Functional enrichment analysis indicated that NTMT1 may contribute to tumor development and progression by regulating pathways involved in cell proliferation and immune response." (PMID 37901469, 2023). "Flow cytometry showed that NTMT1 knockdown promoted tumor cell apoptosis." (PMID 37901469, 2023). "This suggests that NTMT1 may play an important regulatory role in the tumor immune microenvironment, but further experimental exploration is necessary to confirm this hypothesis." (PMID 37901469, 2023). "Since knockdown of siNTMT1-2 could more effectively inhibit the expression of NTMT1 and the proliferation of tumor cells, siNTMT1-2 was used for further study in subsequent experiments." (PMID 37901469, 2023). "In particular, NTMT1 expression is significantly and negatively correlated with 14 functional states in UM, suggesting that it may act as a potential tumor suppressor in UM." (PMID 37901469, 2023). "Conversely, other studies display evidence pointing towards a tumour suppressive function of NTMT1." (PMID 32680559, 2020). "For instance, NTMT1 knockdown significantly enhances the sensitivity of breast cancer cell lines to both etoposide treatment and γ-irradiation, increases proliferation rate, invasive potential, anchorage-independent growth, as well as, xenograft tumor size, and tamoxifen sensitivity." (PMID 37901469, 2023). "This suggests that NTMT1 may act as a tumor suppressor in some contexts." (PMID 37901469, 2023). "Additionally, significant differences in the methylation levels of NTMT1 were observed between various tumor tissues and normal tissues, indicating that NTMT1 may play a crucial regulatory role in tumorigenesis." (PMID 37901469, 2023). "Several genes splicing events, including KIAA1715/56096/AP, ZNF567/49415/AP, NTMT1/87861/AP, ANAPC15/17570/AD, SRPK2/81284/ES, MTMR11/7413/AP, FNIP2/70999/AP, and TNC/87336/ES, differed significantly between tumor and normal samples." (PMID 31552163, 2019). "Furthermore, our findings indicate that NTMT1 expression does not affect the prognosis of these tumor types, highlighting the complexity of NTMT1’s role in regulating tumorigenesis." (PMID 37901469, 2023).
NTMT1 also shares sentences with these, for which no sentence is quoted: adenoma (1 paper); alcoholic hepatitis (1); Alzheimer disease (1); amyotrophic lateral sclerosis (1); bladder urothelial carcinoma (1); breast adenocarcinoma (1); breast tumors (1); cholangiocarcinoma (1); Cognitive impairment (1); colon adenocarcinoma (1); esophageal carcinoma (1); glioblastoma multiforme (1); Lewis Lung Carcinoma (1); lung adenocarcinoma (1); lung squamous cell carcinoma (1); oral squamous cell carcinoma (1); pheochromocytoma and (1); prostate adenocarcinoma (1); rectum adenocarcinoma (1); retinal detachment (1); retinoblastoma (1); stomach adenocarcinoma (1); thyroid carcinoma (1); uterine corpus endometrial carcinoma (1).